HNF1A (HNF1 homeobox A)
Description:
Transcriptional activator that regulates the tissue specific expression of multiple genes, especially in pancreatic islet cells and in liver (By similarity). Binds to the inverted palindrome 5'-GTTAATNATTAAC-3'. Activates the transcription of CYP1A2, CYP2E1 and CYP3A11 (By similarity). (Microbial infection) Plays a crucial role for hepatitis B virus gene transcription and DNA replication. Mechanistically, synergistically cooperates with NR5A2 to up-regulate the activity of one of the critical cis-elements in the hepatitis B virus genome enhancer II (ENII).
Synonyms: HNF-1-alpha; HNF-1A; LFB1; TCF-1; TCF1; HNF1; HNF1α; HNF1alpha; IDDM20; MODY3
Tractability: PROTAC: UniProt records ubiquitination sites on it.
Target class: Transcription factor
Gene: Protein-coding gene on chromosome 12 (120,978,543 to 121,002,512, forward strand). Ensembl gene ENSG00000135100.
Subcellular location: Nucleus
Subcellular location (Human Protein Atlas): Nucleoplasm
Pathways (Reactome):
Developmental Biology: Regulation of gene expression in beta cells
Gene Ontology:
Molecular function: DNA binding; DNA-binding transcription factor activity; protein binding; protein dimerization activity; transcription cis-regulatory region binding; DNA-binding transcription activator activity, RNA polymerase II-specific; DNA-binding transcription factor activity, RNA polymerase II-specific; RNA polymerase II cis-regulatory region sequence-specific DNA binding; chromatin binding; double-stranded DNA binding; identical protein binding; sequence-specific DNA binding; transcription coactivator binding; transcription coregulator binding
Biological process: D-glucose import across plasma membrane; glucose homeostasis; positive regulation of DNA-templated transcription; positive regulation of transcription initiation by RNA polymerase II; regulation of pronephros size; regulation of transcription by RNA polymerase II; renal D-glucose absorption; positive regulation of transcription by RNA polymerase II; apoptotic nuclear changes; cellular response to glucose stimulus; cellular response to L-leucine; cellular response to rapamycin; insulin secretion; liver development; negative regulation of apoptotic process; negative regulation of miRNA processing; negative regulation of transcription by RNA polymerase II; pancreas development; positive regulation of ATP biosynthetic process; positive regulation of gene expression; positive regulation of insulin secretion; positive regulation of mitochondrial membrane potential; positive regulation of phosphatidylinositol 3-kinase/protein kinase B signal transduction; regulation of NADP metabolic process; transcription by RNA polymerase II
Cellular component: cytoplasm; nucleus; protein-containing complex; chromatin; photoreceptor outer segment; pronucleus; transcription regulator complex
Genetic constraint (gnomAD): Loss-of-function variants: 21 observed, 63.37 expected, observed/expected ratio (o/e) 0.33, 90% interval 0.23 to 0.48. The upper end of that interval is the gene's LOEUF score, 0.48, which puts it in group 2 of 6, group 1 being the genes least tolerant of losing a copy. Missense variants: 687 observed, 854.29 expected, observed/expected ratio (o/e) 0.8, 90% interval 0.75 to 0.86. Synonymous variants: 374 observed, 379.07 expected, observed/expected ratio (o/e) 0.99, 90% interval 0.91 to 1.08.
Gene-disease validity (ClinGen):
ClinGen rates the evidence that HNF1A causes each of these diseases.
monogenic diabetes (autosomal dominant): Definitive. Diabetes mellitus that is caused by mutations in a single gene.
Cancer hallmarks: invasion and metastasis (suppresses); suppression of growth (promotes); escaping programmed cell death (suppresses)
Homologues: Orthologues: chimpanzee HNF1A (99% identical), pig HNF1A (97% identical), dog HNF1A (97% identical), guinea pig HNF1A (96% identical), mouse Hnf1a (95% identical), rat Hnf1a (94% identical), macaque HNF1A (93% identical), tropical clawed frog hnf1a (65% identical). Paralogues in human: HNF1B (49% identical).
Diseases named in the same sentence as HNF1A in open-access papers:
HNF1A is named in the same sentence as 217 diseases in open-access papers, as found by Europe PMC text mining. Sharing a sentence is not in itself a finding about the gene and the disease. The quoted sentences say what the papers report.
diabetes (282 papers, 2007 to 2026). "BACKGROUND: HNF1A-MODY is a subtype of monogenic diabetes caused by mutations in the hepatocyte nuclear factor-1 homeobox A (HNF1A) gene." (PMID 41749365, 2026). "ACE2 levels were increased with a diagnosis of hypertension or diabetes, particularly in females, and were influenced by variants in genes associated with diabetes (HNF1A and HNF4A)." (PMID 41054850, 2025). "Mutations in HNF1A are associated with diabetes development, especially in monogenic forms of the disease." (PMID 40004501, 2025). "Unregulated diabetes can develop into congenital hyperinsulinism, diabetes mellitus, and diabetic nephropathies, all known to be associated with HNF1A and HNF4A genes." (PMID 39786569, 2025). "The pathophysiological mechanisms of HNF4A-related diabetes resemble those of mutations in the Hnf1α gene." (PMID 40149950, 2025). "MODY3 is known to be a largely monogenic trait caused by mutations to the transcription factor HNF1A that impact beta cell function and diabetes in general." (PMID 40504147, 2025). "For instance, HNF1A is reported to play a minor role in the pathogenesis of Type 2 diabetes mellitus in Brazilian individuals, while HNF1A mutations are the most common cause of MODY in Europe, North America, and Asia." (PMID 41376825, 2025). "Mutation in HNF1A is also known to cause a monogenic form of diabetes and polymorphism has been linked to risk of GDM." (PMID 41256167, 2025). "ACE2 levels were associated with the loci of diabetes-associated genes HNF1A and HNF4A at GWAS and RVAS." (PMID 41054850, 2025). "For example, the HNF1A (hepatocyte nuclear factor 1 homeobox A) locus (top SNP - rs1169284, ∆Age association p-value=3.0*10–23) is associated with diabetes and cancer." (PMID 40497443, 2025). "Analysis of candidate cis-regulatory elements (cCREs) has shown that some diabetes-associated variants reduce chromatin accessibility at binding sites for transcription factors such as HNF1A and HNF4A, thereby impairing maintenance of a functional phenotype." (PMID 41584842, 2025). "In the only observational study evaluating other than GCK-MODY variants of monogenic diabetes, the median GA at delivery in women diagnosed with HNF1A-MODY was significantly lower compared to GCK(+) individuals—39 weeks vs. 40 weeks, respectively, (p = 0.02)." (PMID 40649834, 2025). "For example, studies have shown that pathogenic variants in the monogenic diabetes gene HNF1A demonstrate significantly lower penetrance in clinically unselected individuals compared to clinically referred probands." (PMID 40970488, 2025). "This case reveals that HNF1A maturity onset diabetes of the young (and probably other causes of monogenic diabetes) can present in sub-Saharan Africa." (PMID 39420387, 2024). "We identify monogenic diabetes variants in 2.4% of individuals and three exome-wide significant (P < 2.6 × 10−6) gene-level associations (HNF1A, MC4R, ATXN2L)." (PMID 38278947, 2024). "Long-term management of infants with an HNF1A variant includes understanding its triphasic nature and the transitions from hypoglycemia to normoglycemia to diabetes." (PMID 39421536, 2024). "HNF1A haploinsufficiency is intimately correlated with the pathogenesis of maturity-onset diabetes of the young (MODY) and hypomorphic HNF1A variants increase the risk of type 2 diabetes mellitus." (PMID 39130628, 2024). "Six HAs were sampled from the liver of a 17-year-old male affected by diabetes and multiple hepatic adenomatosis harboring the heterozygous pathogenic germline variant c.815G>A, p.(Arg272His) in HNF1A, which has a dominant negative effect." (PMID 39408812, 2024). "To date, more than 40 monogenic diabetes subtypes have been described, with those caused by mutations in HNF1A and GCK genes being the most prevalent." (PMID 39408828, 2024). "The patient also mentioned that her eldest daughter was diagnosed with diabetes at the age of 11, and a confirmed heterozygous mutation was identified in the HNF1A gene." (PMID 39055415, 2024).
diabetes (continued). "Of note, mutations in two members of this family, HNF4A and HNF1A, are known to cause Maturity Onset Diabetes of the Young (MODY) – MODY1 and MODY3 respectively." (PMID 38909044, 2024). "Mutations in Hnf1a are responsible for HNF1A-MODY (MODY3 – Maturity Onset Diabetes of the Young), the most prevalent form of monogenic diabetes." (PMID 38825059, 2024). "Heterozygous carriers of the HNF1A mutation experience a gradual decline in β-cell function, leading to the onset of diabetes in early adulthood." (PMID 39055415, 2024). "A more complicated example is the missense variant (HNF1A):c.441C>A (p.His147Gln), which causes an inherited type of diabetes (maturity-onset diabetes of the young—MODY type 3)." (PMID 38409211, 2024). "HNF1A is also involved in increased susceptibility to polygenic forms of diabetes, such as type 2 diabetes (T2D) and gestational diabetes (GD), while its possible role in type 1 diabetes (T1D) is not known." (PMID 37509590, 2023). "Maturity-onset diabetes of the young type 3 (MODY3) is a specific type of diabetes mellitus with inherited impairment of the islet β cell function due to the mutation in the hepatocyte nuclear factor 1α (HNF1α) gene." (PMID 37197360, 2023). "HNF1A gene variants are associated with a monogenic form of diabetes (HNF1A-MODY) or an increased risk for type 2 diabetes." (PMID 37908230, 2023). "The “monogenic diabetes” gene group contains HNF1A, GCK, RFX6, and ABCC8, which harbor variants that cause MODY." (PMID 37292813, 2023). "A custom exome-based panel including genes associated with monogenic diabetes detected a likely pathogenic variant in HNF1A (NM_000545.5: c.526 + 1G > A) confirming the diagnosis of Maturity Onset Diabetes of the Young (MODY)." (PMID 37353797, 2023). "Variant c.1562G>A (p.Arg521Gln) in ABCC8 was detected in a compound heterozygous state with a pathogenic variant of the HNF1A gene in a diabetes patient and his mother." (PMID 36836406, 2023). "Despite the strong association between HNF1A deficiency and human diabetes, the mechanisms by which HNF1α regulates mature human islet cell function remain incompletely understood." (PMID 37943614, 2023). "All patients with GCK or HNF1A heterozygous variants had a parent with IFG or diabetes who carried the same variant." (PMID 36178555, 2023). "The discovery of a transcriptional stabilizer of HNF1A that has a selective function in β cells therefore provides a lead to dissect cell-specific genetic mechanisms underlying HNF1A haploinsufficient diabetes." (PMID 36202974, 2022). "Our studies also highlighted significant eTWAS for T2D, including PCBD1, which is mutated in a syndrome that includes monogenic diabetes, and encodes a co-factor of HNF1A, an established monogenic diabetes gene." (PMID 36109769, 2022). "In fact, published meta-analyses reported especially significant signals of HNF1A association with T2D and diabetes related serum biomarkers." (PMID 35109885, 2022). "In this study based on ascertainment of participants by genotype rather than clinical presentation, one-third of the heterozygous carriers of the HNF1A p.(Gly292fs) variant were free of diabetes at the age of 33, and 13% at the age of 50 years." (PMID 34951657, 2022). "HNF1A mutations cause a monogenic form of diabetes called maturity-onset diabetes of the young (MODY), and HNF1A single-nucleotide polymorphisms are associated with the development of type 2 diabetes." (PMID 35328643, 2022). "Within this specific mutation, it is already known that approximately 60% of HNF1A individuals developed diabetes until 25 years old, 80% until 35 years and 95% until 55 years." (PMID 35822264, 2022). "Mutations affecting the DNA-binding domain or truncating mutations are associated with the earlier onset of diabetes in HNF1A-MODY patients." (PMID 35918471, 2022). "Heterozygous mutations in GCK or HNF1A are the commonest causes of monogenic diabetes in European populations." (PMID 35618782, 2022).
diabetes (continued). "Here, we review the current understanding of HNF1A in multiple organs, including the pancreas, and discuss how HNF1A mutations contribute to the pathogenesis of diabetes, primarily focusing on beta cell dysfunction." (PMID 35328643, 2022). "Kaplan-Meier analysis demonstrated that the penetrance of diabetes for pathogenic HNF1A variants was lower in the family members, the Geisinger cohort, and UK Biobank compared to the HNF1A-MODY probands (log rank test, all p < 3 × 10−9)." (PMID 36257325, 2022). "The sequencing of 354 Danish GDM patients revealed five diabetes-susceptible variants of HNF1α in seven HNF1α mutation carriers." (PMID 35299962, 2022). "Maturity-onset diabetes of the young due to hepatocyte nuclear factor-1 alpha variants (HNF1A-MODY) causes monogenic diabetes." (PMID 34939081, 2022). "Previously, HNF1A mutations were identified in diabetes, and their functional effect was validated; however, only very few studies have suggested that HNF1A mutations identified in HCC are associated with the development and progression of HCC." (PMID 35327967, 2022). "Its diagnostic accuracy has been tested on large cohorts of cases with diabetes carrying different variants in the HNF1A gene." (PMID 34939081, 2022). "MODY is monogenic diabetes caused by a single gene mutation of either HNF-1α, HNF-1β, HNF-4α, HNF-1β, glucokinase, PAK4, KLF11, neurogenic differentiation 1 (neuroD1), and insulin (INS)." (PMID 35956399, 2022). "We hope this review will provide a valuable reference for the precise and individualized treatment of diabetes caused by abnormal HNF1α by summarizing the clinical heterogeneity of blood glucose abnormalities caused by HNF1α mutation." (PMID 35299962, 2022). "Comparing the age of diabetes induced by HNF1α mutation in the literature revealed the age of onset of diabetes was generally 10-16 years." (PMID 35299962, 2022). "We now show that HASTER is a cell-specific cis-acting transcriptional stabilizer of HNF1A and demonstrate that disruption of this function causes diabetes mellitus in mice." (PMID 36202974, 2022). "Haploinsufficient mutations in HNF1A homeobox A (HNF1A), encoding a homeodomain transcription factor, cause diabetes mellitus." (PMID 36202974, 2022). "HNF1α was found to inhibit α cell characteristics in modeling monogenic diabetes using human embryonic stem cells through mutations in HNF1α." (PMID 35299962, 2022). "Genes implicated in monogenic diabetes include several encoding transcription factors involved in pancreatic beta cell development (e.g. HNF1A, HNF1B, HNF4A, PDX1, GATA4, GATA6)." (PMID 35618782, 2022). "We hope our review will facilitate a more comprehensive understanding of hyperglycemia caused by HNF1α mutation and will be useful for accurate diagnosis and treatment of diabetes, especially the hyperglycemia caused by HNF1α." (PMID 35299962, 2022). "A recent case study of cadaveric human islets from a 33-year-old HNF1A-MODY donor with a heterozygous mutation (+/T260M) in the HNF1A DNA-binding domain and with a 17 years history of diabetes also showed an increase in the ratio of α- to β-cells." (PMID 35918471, 2022). "Children exposed to high glucose levels in the uterus who inherit HNF1A mutation from their mother have an earlier onset of diabetes (5–10 years before) than those who inherit the mutation from their father." (PMID 35052457, 2022). "A 39-year-old asymptomatic woman, with atypical diabetes diagnosed at age 17, has a confirmed HNF1A mutation on exon 2 (c.392G>A, p.R131Q), classified as Pathogenic by the ACMG guidelines." (PMID 35551682, 2022). "We have found that over one‐quarter of this subset of participants were positive for monogenic diabetes, mainly positive for HNF1A mutation." (PMID 35822264, 2022). "In this study, we analyzed N-glycan fucosylation of plasma glycoproteins in 320 individuals with diabetes and clinical features matching those at risk of HNF1A-MODY, using a newly developed LC-based workflow." (PMID 33765222, 2021).